ATF7 (activating transcription factor 7)
Diseases named in the same sentence as ATF7 in open-access papers:
ATF7 is named in the same sentence as 32 diseases in open-access papers, as found by Europe PMC text mining. Sharing a sentence is not in itself a finding about the gene and the disease. The quoted sentences say what the papers report.
gastric cancer (5 papers, 2021 to 2025). A primary or metastatic malignant neoplasm involving the stomach. "Studies have shown that miRNA-103A-3p can significantly promote the proliferation of gastric cancer cells by targeting and inhibiting the expression of ATF7." (PMID 34787047, 2021). "miR-103a-3p can also promote gastric cancer cell proliferation by targeting ATF7." (PMID 34307670, 2021).
breast carcinoma (4 papers, 2015 to 2021). "Notably, ATF7 expression was positively associated with PCAT18 expression in both breast cancer tissues and TNBC-specific specimens." (PMID 34787047, 2021). "In the present study, low expression of ATF7 was found in breast cancer (n = 1104) specimens compared to normal subjects (n = 113) and was also verified in TNBC tissues (n = 317) compared to non-TNBC tissues (n = 4119)." (PMID 34787047, 2021). "The PCAT18/miR-103a-3p/ATF7 signaling axis was also demonstrated in a lung metastasis model of breast cancer." (PMID 34787047, 2021). "For example, Erb-b2 receptor tyrosine kinase 2 gene (ERBB2, synonym: HER2) was upregulated in one breast cancer sample containing the ATF7-SPATS2 fusion." (PMID 29299133, 2017). "We next examined the ability of ATF7-TRAIL to sensitize MDA-MB-231 cells in vivo using an orthotopic breast cancer xenograft model in mice." (PMID 25849628, 2015). "Our data demonstrated that the cytotoxic and caspase-3/7-inducing activities and the antitumor potency (as determined by an orthotopic breast cancer xenograft model in immunodeficient mice) of the ATF7-TRAIL and the GCN4-TRAIL constructs were roughly similar." (PMID 25849628, 2015). "Indeed, PCAT18 upregulation mediated the improvement in lung metastasis in breast cancer, which was also aided by injection of miR-103a-3p mimic, followed by the decline in ATF7." (PMID 34787047, 2021). "ATF7-TRAIL at the concentrations as low as 10 ng/ml was highly cytotoxic to breast carcinoma MDA-MB-231, prostate carcinoma PPC-1, and lung carcinoma SK-MES-1 cells, despite the fact that some of these cells have been considered resistant to TRAIL-mediated apoptosis." (PMID 25849628, 2015).
colitis (2 papers, 2025). Inflammation of the colon. "To assess the physiological relevance of ATF7‐mediated regulation of mitophagy in vivo, we employed DSS‐induced acute colitis models in intestinal epithelial cell‐specific ATF7‐deficient and PINK1‐deficient mice." (PMID 40903840, 2025). "Loss of ATF7 disrupts mitochondrial homeostasis, increases ROS production, and exacerbates mucosal inflammation in colitis." (PMID 40903840, 2025). "Consistent with our in vitro results, ATF7 deficiency led to elevated ROS levels in DSS‐induced colitis." (PMID 40586859, 2025). "We demonstrate that ATF7 deficiency leads to impaired mitophagy, exacerbating colitis." (PMID 40586859, 2025). "During disease progression, ATF7−/− mice exhibited greater weight loss, more pronounced colonic shortening, elevated disease activity index scores, and higher histopathological injury scores, indicating exacerbated colitis severity upon ATF7 loss." (PMID 40903840, 2025). "To validate the role of ATF7 in regulating mitochondrial function, we utilized mice with intestinal epithelial cell‐specific deletion of ATF7 and induced colitis using DSS." (PMID 40586859, 2025). "To explore the transcriptional consequences of ATF7 loss in vivo, we performed RNA sequencing on colonic tissues from wild‐type (WT + DSS) and intestinal epithelial‐specific ATF7 knockout mice (ATF7−/− + DSS) subjected to DSS‐induced colitis." (PMID 40903840, 2025). "Thus, future studies employing conditional knockout or cell‐specific rescue strategies in these alternative cellular compartments would help clarify the comprehensive cellular and molecular landscape influenced by ATF7 signalling in colitis." (PMID 40903840, 2025). "In vivo, intestinal epithelial cell‐specific knockout of ATF7 or PINK1 exacerbated dextran sulfate sodium‐induced colitis, with greater epithelial injury, elevated cytokine production, and transcriptional activation of TNF, NF‐kappaB, and inflammatory bowel disease signalling pathways." (PMID 40903840, 2025). "Using intestinal epithelial‐specific knockout mouse models, we further validated these findings in vivo by demonstrating that ATF7 deficiency significantly impairs mitochondrial integrity, exacerbates ROS accumulation, and worsens intestinal inflammation in response to DSS‐induced colitis." (PMID 40903840, 2025). "To validate these observations in a physiologically relevant context, we utilised intestinal epithelial cell‐specific knockout mouse models for ATF7 and PINK1, employing the DSS‐induced colitis model." (PMID 40903840, 2025).
colon cancer (2 papers, 2021). "ATF7 is significantly correlated with the prognosis of colon cancer and is involved in the proliferation, apoptosis, and survival of various tumor cells." (PMID 34787047, 2021).
hepatocellular carcinoma (2 papers, 2022 to 2024). A malignant tumor that arises from hepatocytes. "HBV regulates the growth of hepatoma cells via mir-304-5p/ATF7/ HSPB1 signal axis." (PMID 35150481, 2022). "In hepatocellular carcinoma (HCC), expression of HSPA1B increased through Hepatitis B virus-mediated activation of ATF7, which accelerated cell proliferation by inhibiting apoptosis." (PMID 38461240, 2024).
Immunodeficiency (2 papers, 2010 to 2013). Failure of the immune system to protect the body adequately from infection, due to the absence or insufficiency of some component process or substance. "If ATF-7 and DAF-19 function in parallel, we could expect a stronger immunodeficiency phenotype in a double mutant of atf-7(lf) and daf-19 relative to the single mutants." (PMID 23505381, 2013).
leukemia (2 papers, 2021 to 2025). A malignant (clonal) hematologic disorder, involving hematopoietic stem cells and characterized by the presence of primitive or atypical myeloid or lymphoid cells in the bone marrow and the blood. "Notably, IRF2BP2 was recently shown to interact and repress the function of the AP1 heterodimer ATF7/JDP2 in leukemia cells." (PMID 39752494, 2025).
myocardial infarction (2 papers, 2021 to 2025). Gross necrosis of the myocardium, as a result of interruption of the blood supply to the area, as in coronary thrombosis. "Furthermore, transcriptomic analysis in swine has described underexpression of the ATF7 gene, which is related to LV remodeling after myocardial infarction." (PMID 34829621, 2021).
Obesity (2 papers, 2018 to 2025). Accumulation of substantial excess body fat. "Some studies have shown that ATF7 ablation prevents diet-induced obesity and insulin resistance." (PMID 39773758, 2025). "For example, we observed associations between functionally annotated rare variants in the gene TACR1 and chronic sinusitis, as well as associations between functionally annotated variants in ATF7 and obesity related diagnoses (results not passing multiple burden threshold)." (PMID 29545597, 2018).
ulcerative colitis (2 papers, 2025). An inflammatory bowel disease involving the mucosal surface of the large intestine and rectum. "Ulcerative colitis is associated with diminished ATF7 expression in intestinal epithelial cells, which compromises PINK1 transcriptional activation and leads to impaired mitophagy, mitochondrial dysfunction, and excessive reactive oxygen species (ROS) accumulation." (PMID 40586859, 2025). "In conclusion, our study provides compelling evidence positioning ATF7 as a central transcriptional regulator connecting mitochondrial quality control with inflammation in ulcerative colitis." (PMID 40903840, 2025). "Given the chronic inflammation and epithelial damage that are hallmarks of ulcerative colitis, this opens new avenues for future research into the broader roles that ATF7 might play in gastrointestinal health and disease." (PMID 40586859, 2025). "Its suppression coincides with the activation of pro‐inflammatory and stress‐related signalling pathways, suggesting that ATF7 may function as a key epithelial‐intrinsic regulator of immune homeostasis and barrier integrity in the context of ulcerative colitis." (PMID 40903840, 2025). "In our study, we have focused on elucidating the roles of Activating Transcription Factor 7 (ATF7) and PTEN‐induced kinase 1 (PINK1) within the context of ulcerative colitis (UC) and its manifestation in intestinal epithelial cells (IECs)." (PMID 40586859, 2025).
inflammatory bowel disease (1 paper, 2025). A spectrum of small and large bowel inflammatory diseases of unknown etiology. "Finally, Gene Set Enrichment Analysis (GSEA) confirmed that the TNF signalling pathway, NF‐κB pathway, and inflammatory bowel disease pathway were significantly activated in ATF7−/− + DSS mice relative to WT + DSS controls, reinforcing the pro‐inflammatory phenotype associated with ATF7 loss." (PMID 40903840, 2025).
intestinal infection (1 paper, 2024). "This transcription factor regulates the transcription factor ATF-7, which together with ELT-2 and DAF-16, regulates the expression of genes related to the host defense and innate immunity in response to intestinal infection, mediated by several C-type lectins or lysozymes." (PMID 38200022, 2024).
liver cancer (1 paper, 2022). An epithelial or non-epithelial malignant neoplasm that arises from the liver. "HBV can enhance the expression of activating transcription factor 7 (ATF7) by downregulating miR-340-5p, which in turn interacts with heat shock protein family A member 1B (HSPA1B), promoting cell proliferation and inhibiting apoptosis, which in turn affects the development of liver cancer." (PMID 36278230, 2022).
myocardial ischemia (1 paper, 2025). A disorder of cardiac function caused by insufficient blood flow to the muscle tissue of the heart. "In myocardial ischemia/reperfusion injury, HNEAP knockout restores DNMT1-mediated ATF7 methylation, reduces cardiomyocyte death, and improves cardiac function." (PMID 40405297, 2025).
infection (17 papers, 2010 to 2025). The state of being infected such as from the introduction of a foreign agent such as serum, vaccine, antigenic substance or organism. "Survival analysis showed that elt-2 knock-down in developing atf-7 mutants only marginally exacerbated infection susceptibility, as in pmk-1 mutants; similar results were observed in worms treated with elt-2 RNAi during adulthood." (PMID 26016853, 2015). "Pathogen‐infection‐induced phosphorylation of ATF7 stimulates the release of ATF7‐G9a from target genes, accompanied by a decrease in repressive histone H3K9me2 levels, leading to elevated gene expression." (PMID 36254813, 2023). "For example, atf-7 can directly regulate the genes of host defense and the anti-inflammatory PMK-1/ATF-7 signaling can contribute to innate immune response to infection." (PMID 35433778, 2022). "We observe that PMK-1-ATF-7 activity regulates a majority of all genes induced by pathogen infection, and observe ATF-7 occupancy in regulatory regions of pathogen-induced genes in a PMK-1-dependent manner." (PMID 30789901, 2019). "The genome-wide regulation through PMK-1– ATF-7 signaling reveals a striking level of control over the innate immune response to infection through a single transcriptional regulator." (PMID 30789901, 2019). "In this study, we show that ATF-7 directly regulates the majority of innate immune response genes upon pathogen infection of C. elegans, and demonstrate that many ATF-7 targets function to promote pathogen resistance." (PMID 30789901, 2019). "Activation of the PMK-1 p38 MAPK pathway in response to pathogen infection results in PMK-1 phosphorylation of ATF-7, leading to a switch in ATF-7 from a transcriptional repressor to an activator." (PMID 23437011, 2013). "However, we found that the expression of mir-233 in the atf-7(gk715) mutant was comparable to that in WT worms after PA14 infection." (PMID 25569229, 2015). "Genetic analysis of resistance of C. elegans to infection by pathogenic Pseudomonas aeruginosa has defined an essential role for a conserved p38 mitogen-activated protein kinase pathway that acts on a CREB/ATF family bZIP transcription factor, ATF-7, in immune responses." (PMID 30789901, 2019). "Following infection to Pseudomonas aeruginosa, ELT‐2 cooperates with the transcription factors SKN‐1 and ATF‐7 (Activating Transcription Factor) to promote the expression of different classes of immune genes." (PMID 36797658, 2023). "Consistent with our transcriptome analysis, we found that the majority of selected targets of PMK-1/ATF-7 and ATFS-1 were upregulated by both PA14 infection and aco-2 RNAi." (PMID 37349299, 2023). "In order to determine the function of atf-7 and skn-1 in the ASPS regulation process, we used atf-7 mutant and skn-1 mutant for PA14 infection experiments." (PMID 35563423, 2022). "Thus one plausible mechanism could be that DAF-19 and ATF-7 bind to a promoter element shared in common among the pathogen-inducible genes, and infection induces the TIR-1 signaling cascade leading to phosphorylation of ATF-7 and transcriptional activation of the targets." (PMID 23505381, 2013). "Whereas PMK-1 mediates multiple responses to environmental stressors, including oxidative stress and pathogen infection, these data suggest that the transcription factor substrates of PMK-1, ATF-7 and SKN-1, confer specificity to PMK-1-mediated responses." (PMID 20369020, 2010). "Of these three transcription factors, we have only obtained a DNA binding site for cTf4, which is, like the DNA binding sites of aTf2, aTf5 and aTf7, not enriched among genes up- or down-regulated during infection." (PMID 27855160, 2016). "Meanwhile, atf-7 RNAi did not influence the expression of mir-233p::gfp in either WT or pmk-1(km25) worms after PA14 infection." (PMID 25569229, 2015).
infection (continued). "Based on these data, we propose that activation of the PMK-1 pathway in response to pathogen infection results in PMK-1 phosphorylation of ATF-7, leading to a switch in the activity of ATF-7 from transcriptional repressor to an activator that facilitates P. aeruginosa-induced gene expression." (PMID 20369020, 2010). "However, their infection-induced expression was not significantly reduced until both skn-1 and atf-7 were disrupted." (PMID 26016853, 2015). "In order to determine whether our observations were specific to infection by P. aeruginosa PA14, we examined the role of ATF-7 in pathogen resistance to two other microbial pathogens that cause lethal infections in C. elegans, Serratia marcescens and Enterococcus faecalis." (PMID 20369020, 2010). "Indeed, survival analysis in atf-7 mutants demonstrated the non-redundant contribution of skn-1 to infection resistance, and further showed no added contribution of elt-2, suggesting that in regulating immune protection elt-2 works with these two regulators but no additional ones." (PMID 26016853, 2015).
tumor (5 papers, 2015 to 2025). "ATF7-TRAIL exhibited a potent anti-tumor activity in both cell-based tests and assays in mice, thereby endorsing its further evaluation in preclinical mouse models." (PMID 25849628, 2015). "At a 5 mg/kg concentration, ATF7-TRAIL caused a decrease in tumor incidence and a 4-fold reduction in tumor size relative to control, thus confirming the potency of our TRAIL formulation." (PMID 25849628, 2015). "Specifically, hepatocytes at the tumor periphery predominantly expressed TFs such as ILF2, ATF7, and RFXANK, while those in the tumor core were enriched for KLF4, EGR1, and HES5." (PMID 40474968, 2025). "To analyze the ATF7-TRAIL apoptotic activity we used caspase 3/7 activation, cell viability, and tumor zenograft assays." (PMID 25849628, 2015). "In solution, ATF7-TRAIL exists solely as a trimer with a Tm of 80°C and is active against cancer cells both in vitro and in vivo, in a mouse tumor xenograft model." (PMID 25849628, 2015). "Combination with chemotherapeutic agents may further enhance the efficacy of ATF7-TRAIL and overcome tumor resistance to TRAIL therapies." (PMID 25849628, 2015). "We also believe that in order to increase the repertoire of potent and safe TRAIL-based anti-tumor agents it would be beneficial to analyze in vivo other fully human leucine-zipper-TRAIL fusion proteins with activity and stability comparable to those of ATF7-TRAIL." (PMID 25849628, 2015).
cancer (4 papers, 2015 to 2025). A tumor composed of atypical neoplastic, often pleomorphic cells that invade other tissues. "One of the targets of miR-340-5p in HCC is ATF7, which is involved in cancer cell proliferation." (PMID 34007276, 2021). "To further confirm that ATF7-TRAIL induced apoptosis in carcinoma cells but not in normal cells, we analyzed the caspases-3/7 activity in TRAIL-treated cells." (PMID 25849628, 2015).
bacterial infections (1 paper, 2016). "RPW-24 was found to protect the worms from bacterial infection by inducing the p38 MAP kinase pathway-mediated response and the transcription factor ATF-7, suggesting the utility of the C. elegans model to discover novel strategies effective in treating bacterial infections." (PMID 27994583, 2016).
ATF7 also shares sentences with these, for which no sentence is quoted: prostate carcinoma (4 papers); bladder cancer (2); cardiac hypertrophy (2); melanoma (2); amyotrophic lateral sclerosis (1); chronic sinusitis (1); colorectal cancer (1); heart disease (1); inflammation (1); Insulin resistance (1); lung carcinoma (1); neuroblastoma (1); renal carcinoma (1); triple-negative breast carcinoma (1).